HGF (hepatocyte growth factor)
Diseases named in the same sentence as HGF in open-access papers (continued):
Sharing a sentence is not in itself a finding about the gene and the disease.
breast carcinoma (continued). "Interestingly nanoparticle-encapsulated EGCG retained its biological activity and blocked hepatocyte growth factor (HGF)-induced intracellular signaling in the breast cancer cell line MBA-MD-231 as potently as free EGCG." (PMID 24212623, 2011). "Neutralization of HGF activity reduced CAF-mediated colony formation of breast cancer cells, suggesting that HGF secreted by CAFs may be the major contributing factor for this differential tumorigenic promoting ability between CAFs and NAFs." (PMID 21249190, 2011). "Activated Stat3 mediates signals downstream of the HGF/c-met pathway, and Stat3 has been shown to be essential for HGF-induced morphogenesis and for invasive behavior driven by c-met in both fibroblasts and breast carcinoma cells." (PMID 21595927, 2011). "Importantly, HGF expression and the tumor promoting activity of NAFs can be induced and fixed to similar levels as those of CAFs by long term co-culturing NAFs with breast cancer MDA-MB-468 cells in a transwell system." (PMID 21249190, 2011). "c-Src kinase and STAT3 activated hepatocyte growth factor expression in breast carcinoma cells." (PMID 20796316, 2010). "With respect to breast carcinomas, the localization of HGF within the mammary gland is less clear." (PMID 20624308, 2010). "Additionally HGF is up-regulated in breast cancer and also released at higher levels by these fibroblasts." (PMID 19152687, 2009). "Pretreatment of breast carcinoma cells with 100 or 200 ng ml−1 HGF caused similar changes in invasiveness (not shown)." (PMID 18941460, 2008). "We set out to verify whether in HGF-exposed breast carcinoma cells, HDACs were important for invasive growth by regulating gene expression, motility and apoptosis, depending on the tumour aggressiveness." (PMID 18941460, 2008). "We have also characterized a Src/Stat3 responsive region on the HGF promoter identifying a Stat3 consensus binding site at nt-95 that has been demonstrated to be required for HGF promoter activation by Src/Stat3 in mouse mammary carcinoma cells." (PMID 17967179, 2007). "In addition, we and others have previously observed frequent over-expression of both HGF and Met in invasive human breast carcinomas." (PMID 17967179, 2007). "However, several other fat-secreted substances have been suggested to provide links between obesity and breast cancer, such as adiponectin, hepatocyte growth factor and IL-6, perhaps through interfering with insulin resistance and estrogen synthesis." (PMID 17010200, 2006). "Furthermore, it was recently demonstrated that HGF in combination with FN prolongs the survival of GM-colony-forming cells and enhanced the adhesion and motility of MTLn3 breast carcinoma cells." (PMID 15717924, 2005). "The mutual interactions mediated by HGF and prostaglandins may possibly be a mechanism regulating malignant behaviour of mammary tumour cells, through tumour–stromal interactions." (PMID 10496342, 1999). "Therefore, HGF could be an intervention target by either medicines or lifestyle changes to improve the prevention and treatment of breast cancer." (PMID 40665092, 2025). "Furthermore, our study found that HGF may mediate the effects of the HLI and BMI on breast cancer risk, which was more pronounced in postmenopausal women." (PMID 40665092, 2025). "Notably, the mediation analysis in UKB-PPP showed that HGF significantly mediated the effects of HLI (27.17%) and BMI (19.79%), as well as a marginally significant mediation effect concerning physical activity measured in MET (20.38%) on breast cancer risk." (PMID 40665092, 2025). "Accordingly, the future direction would test the effect of HGF or other factors in 3D cell culture technologies to generate mammary cells not only as a new research tool in basic biomedicine researches and drug screening, but also as potential therapeutics to treat breast cancer." (PMID 37168728, 2023).
breast carcinoma (continued). "The HSPGs GPC1 and SDC1, overexpressed in a high percentage of breast cancer pathologies, enhance the mitogen effects associated with heparin-binding growth factors like Basic Fibroblast Growth Factor (FGF2), HBEGF and Hepatocyte growth factor (HGF), promoting cell proliferation." (PMID 33494442, 2021). "The HGF pathway may also play a role in breast cancer disparities by race." (PMID 34344422, 2021). "This led to the hypothesis that HGF acts as a mitogen in female breast cancer." (PMID 32188473, 2020). "Moreover, the important role of CUX1/FGF1/HGF signalling in promoting cell proliferation, migration and tube formation in vascular endothelial cells was strongly associated with the DPPA‐induced inhibition of tumour growth and angiogenesis in breast cancer." (PMID 30010249, 2018). "Whether matriptase plays additional non-HGF/c-Met mediated roles in IBC tumorigenicity and whether the observed link between expression/loss of matriptase and E-cadherin in IBC is correlational or causal in breast cancer remains to be explored." (PMID 27528224, 2016). "Finally, the data of our translational research suggest that ET-1 and HGF may create a signaling network in bone metastasis from breast carcinoma." (PMID 27187355, 2016). "Amplification of MET may also be important in other molecular subtypes of breast cancer: in a study of 130 Her2-positive breast cancers, both MET and HGF amplification were associated with trastuzumab failure and patients with MET amplified tumours had a shorter time to progression." (PMID 25887320, 2015). "Higher ELF5 expression in luminal A, but not B breast cancers, was broadly associated with the same five functional networks identified in the PyMT/Elf5 model: HGF and IL4, invasive phenotype, monocytes, immune system involvement, inflammation and the interferon response." (PMID 26717410, 2015). "In addition to favouring epithelial dissociation via E-Cadherin downregulation/internalisation, there is some evidence that HGF/c-Met signalling contributes to breast cancer progression by promoting cancer cell adhesion to components of the extracellular matrix." (PMID 25887320, 2015). "Moreover, the significant antitumor efficacy of new tyrosine kinase inhibitor (TKI) XL-184 (cabozantinib maleate), which targets MET and VEGFR-2, for bone metastasis in patients with prostate or breast cancers also shows the importance of HGF/MET signaling in bone metastasis." (PMID 25186085, 2015). "Experiments performed using c-Met inhibitor suggested HGF/c-Met crosstalk between ASCs and breast cancer cells could have an important role in promoting cancer cells migration and tumor growth, making breast cancer cells highly invasive and successful in metastatic dissemination." (PMID 24327602, 2014). "The potential involvement of HGF/Met in Src/ezrin-mediated tumour angio/lymphangiogenesis is consistent with our recent finding demonstrating Src/ezrin co-operation increased Met activation and extracellular matrix degradation, characteristic of an invasive phenotype in breast cancer." (PMID 25231728, 2014). "Also, in breast cancer cells, HGF can induce EMT and enhance cell motility and invasion." (PMID 24098477, 2013). "Our coculture results established a fold-change increase in HGF signaling in premalignant, basal-like microenvironments; however, if these changes are essential for basal-like breast carcinogenesis, then they should also be present in invasive basal-like breast cancers." (PMID 24025166, 2013). "HGF is a powerful motogen able to promote proliferation, invasion, and migration of epithelial cells by binding to its tyrosine kinase receptor c-met as well as modulating expression and function of TJ molecules in human breast cancer cell lines and decreasing trans-epithelial resistance." (PMID 22559840, 2012).
breast carcinoma (continued). "Our findings on HGF-mediated recovery, extend the previously published results to mammary epithelial cells and ErbB2 mammary tumor cells, emphasizing the fact that molecular events present in non tumorigenic cells could be retained during tumor growth and become the basis for drug resistance." (PMID 23028720, 2012). "Clearly, therefore, the potential therapeutic use of TSA should take into account the differences in the aggressiveness of breast carcinoma cells and the tumour microenvironment at the secondary growth site, where HGF might contribute to creating a permissive niche for homing." (PMID 18941460, 2008). "MCF-7 breast cancer cells yielded comparable results, with a significant increase in TNT observed in cells treated with TGFβ-1, IL-6, and HGF." (PMID 41750361, 2026). "In breast cancer, they secrete cytokines that enhance androgen synthesis, stimulate growth factors like FGF and HGF, and drive excessive epithelial cell proliferation." (PMID 40230452, 2025). "First, CCR2-KO or Merestinib treatment alone reduced the growth and survival of mammary carcinomas and inhibited M2 macrophage recruitment, indicating disruptions to CCL2 and HGF signaling with inhibition of CCR2 or MET." (PMID 40736024, 2025). "CCL2 and HGF co-treatment enhanced breast cancer cell growth, survival, and invasiveness over individual CCL2 or HGF treatment." (PMID 40736024, 2025). "Across all types of breast cancers, at least 20–30% of cases show c-MET overexpression, and HGF and c-MET are often co-expressed in invasive breast cancers." (PMID 40361420, 2025). "In summary, CCL2 and HGF co-treatment enhanced proliferation, survival, and invasion in DCIS.com and HCC1937 breast cancer cells over CCL2 or HGF alone, with some differences in responsiveness to CCL2 and HGF between the cell lines." (PMID 40736024, 2025). "Among them, the HGF/c-MET pathway is closely related to cancer metastasis and can promote breast cancer resistance to tamoxifen through the EZH2/HOTAIR-MIR-141/200A feedback signaling pathway." (PMID 40860340, 2025). "While alterations in glutamine/glutamate have been reported in breast cancers, this pathway was of lower impact than glucose metabolism in CCL2/HGF co-treated cells." (PMID 40736024, 2025). "Overall, these data indicated that CCL2, HGF and CCL2/HGF co-treatment led to changes in overlapping and unique metabolic pathways in breast cancer cells." (PMID 40736024, 2025). "The HGF (hepatocyte growth factor)/MET pathway plays an important role in normal mammary development and various breast cancer progression processes, including migration, invasion, and tubulogenesis." (PMID 40560045, 2025). "Here, we showed that CCL2/HGF co-treatment increased cell growth, survival, and invasion in DCIS.com and HCC1937 breast cancer cells over CCL2 or HGF treatment alone." (PMID 40736024, 2025). "In breast cancer, signaling axes such as EGFR, IGF, TGFβ, and HGF/c-Met critically regulate CSC expansion, particularly in aggressive subtypes like triple-negative tumors." (PMID 41373619, 2025). "The results revealed a notable downregulation of AVPR1A, FEZ1, HGF, GSN, NEDD9, and EGR3 expression in the breast cancer cell lines (MCF7, BT-474, SK-BR-3, MDA-MB-231) when compared to the normal mammary epithelial cell line (MCF-10A)." (PMID 38756447, 2024). "In luminal breast cancer, PIK3CB, ACVR18, HGF, and ERG were identified as the key genes with varying mutation frequencies between the luminal HER2-low and luminal HER2-0 subgroup." (PMID 39648226, 2024). "Hepatocyte growth factor (HGF) is recognized for its role in promoting the development and progression, including metastasis, of breast carcinoma." (PMID 39203892, 2024). "For example, addition of hepatocyte growth factor (HGF) induced resistance to epidermal growth factor inhibition in lung cancer cells, while heregulin induced resistance to HER2 kinase inhibition in breast cancer cells." (PMID 39513002, 2024).
breast carcinoma (continued). "Extensive research links CAFs to breast cancer progression, with studies showing that CAFs secrete SDF-1/CXCL12 and HGF, both of which promote breast cancer growth and metastasis." (PMID 38533507, 2024). "The mRNA expression levels for eight pro-angiogenic genes [VEGFA, HGF, FGF1, FGF2, ANGPT1, ANGPT2, PDGFA, and PDGFB] were obtained from the METABRIC (Molecular Taxonomy of Breast Cancer International Consortium) dataset available at cBioPortal public domain." (PMID 39302921, 2024). "HGF activates c-Met on tumor cells, leading to enhanced metastasis, while SDF-1 facilitates tumor growth and angiogenesis through the CXCR4 receptor on breast carcinoma cells." (PMID 38533507, 2024). "This is important as MET pathway, including MET receptor and its ligand, hepatocyte growth factor (HGF), has a key role in cancer cell migration and metastasis and is an established target of breast cancer therapy." (PMID 36690660, 2023). "The encapsulated form of EGCG retained its potency, effectively inhibiting the hepatocyte growth factor (HGF) and the resulting activation of cell signaling pathways that contribute to cell invasion in MDA-MD-23 breast cancer cells." (PMID 38129839, 2023). "In the literature, FB were also reported to induce EMT in breast cancer cells by the secretion of activating growth factors like TGF-β1, EGF, PDGF, HGF, and MMP." (PMID 37781195, 2023). "The SLIT2/ROBO1 pathway inhibits cell invasion by interacting with E-cadherin and β-catenin in breast cancer and colorectal cancer, whereas in liver cancer, SLIT2/ROBO1 specifically inhibits hepatocyte growth factor (HGF)–mediated cell migration." (PMID 36498797, 2022). "We investigated the role of CDCP1 in human breast cancer cells and found that the CDCP1-SRC axis enhanced the HGF-induced formation of lamellipodia or membrane ruffles, leading to the promotion of cell migration and invasion." (PMID 35085554, 2022). "Another interesting study suggested that the HGF/MET signaling pathway in CAFs was activated, and secreted HGF conferred gefitinib resistance in breast cancer by increasing MET phosphorylation." (PMID 36359776, 2022). "In metastatic human breast cancer cell line MDA-MB-231, which highly expresses the HGF receptor MET and CDCP1, we show that CDCP1 knockdown attenuated HGF-induced MET activation, followed by suppression of lamellipodia formation and cell migration/invasion." (PMID 35085554, 2022). "A recent study reported that the VEGF, IL-8, HGF, and IGF-I expression in ASCs resided in breast cancer tissues, and was twofold higher in patients than controls." (PMID 36077676, 2022). "Previous studies have shown that HGF and MET expression are elevated and correlated with progression and poorer prognosis in breast cancer patients." (PMID 34381422, 2021). "In another breast cancer study, levels of IL-7, IL-8, IL-13, macrophage migration inhibitory factor (MIF), and TNF-β were increased, whereas those of CTACK, G-CSF, HGF, IL-1β, and TNF-α were decreased after IORT exposure." (PMID 34641806, 2021). "Ectopic expression of SPINT1 or SPINT2 in fibroblasts induced a reduction in HGF levels, thus ablating the HGF-mediated metastatic influence on MDA-MB-231 breast cancer cells." (PMID 34381422, 2021). "Regarding the remaining proteins, HGF, GRO-1, and IGF-1 have been found to stimulate the adhesion of breast cancer, gastric cancer, and multiple myeloma cells, respectively; in all these studies, the activity of these proteins was dependent on β1-integrin." (PMID 33921783, 2021). "HER2-positive basal-like breast cancers can activate MET with expression of its ligand, the hepatocyte growth factor (HGF), particularly in liver where HGF is high." (PMID 33772089, 2021). "In the present study, HGF and CXCL12 tumor expression identified male breast cancer patients with good prognosis." (PMID 32188473, 2020).
breast carcinoma (continued). "Activation of the HGF-MET signalling pathway promotes metastasis of various tumors, including CRC, breast cancer, ovarian cancer, lung cancer and liver cancer." (PMID 32843066, 2020). "The hepatocyte growth factor (HGF)/c-MET axis and the stromal cell-derived factor-1 (CXCL12)/C-X-C chemokine receptor type 4 (CXCR4) axis are prognostic in women with breast cancer." (PMID 32188473, 2020). "Remarkably, the prognostic value of HGF and c-MET is contradictory to the findings in female breast cancer." (PMID 32188473, 2020). "Activation of the HGF/MET signalling pathway has been reported to lead to the occurrence and metastasis of a variety of tumors, including CRC, breast cancer, ovarian cancer, lung cancer, and liver cancer." (PMID 32843066, 2020). "HGF and CXCL12 tumor expression appear to identify male breast cancer patients with a relatively good prognosis." (PMID 32188473, 2020). "Using the breast cancer cell line MDA-MB-453 and GBM cell line U-373, treatment with cMET receptor ligand hepatocyte growth factor/scatter factor was shown to impart resistance to doxorubicin/adriamycin and cisplatin." (PMID 31215502, 2019). "As the upstream of FGF1/HGF signaling pathway, CUX1 has been reported to contribute to the progression of luminal and basal breast cancer, help distinguishing Her2 subtype of breast cancer." (PMID 31480430, 2019). "In this sense, secretion of hepatocyte growth factor (HGF) and IL-6 by CAFs has been related to lapatinib resistance in HER2+ breast cancer and tamoxifen resistance, respectively." (PMID 31086100, 2019). "A crosstalk mediated by HGF/c-MET between ASCs and breast cancer cells increased the invasion ability of cancer cells and their growth rate." (PMID 30335754, 2018). "To this end, we activated MET and TGFβ signaling pathways with HGF and TGFβ1, respectively, and tested their influence on TGFBR2 or MET expression in the model cell line MCF10A as well as in basal‐like breast cancer cell lines HS578T and HCC1143." (PMID 30004628, 2018). "Hepatocyte growth factor (HGF) transcriptional activation of LEF1 was shown to be dependent on AKT/NF-κB signaling in liver and breast carcinoma cell lines." (PMID 29535816, 2018). "We determined the impact of HGF stimulation and BFE treatment on the aggressive motile nature of these breast cancer cells every 60 min over a 6 h period." (PMID 30314527, 2018). "Higher C‐ets‐1 and lower miR‐128‐3p expression levels intensify MET signaling and thereby suggest TGFβ1 as a regulator of HGF‐mediated migration in MCF10A and breast cancer cells." (PMID 30004628, 2018). "Flow cytometry examination in U87-MG (human glioblastoma) and MDA-MB-231(human breast cancer) cell lines, which have moderate level and low level expression of c-MET, respectively, confirmed the specific binding capacity of rh-HGF to c-MET." (PMID 28485003, 2017). "BMP-4 is considered as an inhibitor of breast cancer cell growth, but can also have a synergistic effect on proliferation of breast cancer cells induced by fibroblast growth factor (FGF), EGF and HGF." (PMID 28733469, 2017). "A similar effect of CTX-III on hepatocyte growth factor (HGF)-stimulated migration and invasion in breast cancer cells has been described." (PMID 29189742, 2017). "Not only is the function of HGF affected by TSP-1, the expression of this anti-angiogenic factor has also been shown to be down-regulated by HGF-c-Met interactions in breast cancer cells, indicating a negative regulatory circuit of TSP1 and HGF." (PMID 29296173, 2017). "Recently, we revealed that herbacetin, a flavonoid aglycon in EH, inhibited HGF/c-Met/Akt signal and HGF-induced motility of human MDA-MB-231 breast cancer cells." (PMID 26976141, 2016). "Hepatocyte-growth factor (HGF) stimulated Twist1 activity, which was shown to positively regulate the MET phenotype to promote breast cancer cell metastasis to bone." (PMID 27782035, 2016).